IL34 (interleukin 34)
Diseases named in the same sentence as IL34 in open-access papers (continued):
Sharing a sentence is not in itself a finding about the gene and the disease.
colitis (6 papers, 2015 to 2025). Inflammation of the colon. "In both rats and mice, IL34 deficiency caused a moderate increase in pathology in the dextran sodium sulphate colitis model." (PMID 40533345, 2025). "Here we report that the absence of expression of IL‐34 in Il34−/− rats and mice leads to an unstable immune phenotype, with production of multiple auto‐antibodies, exacerbated under inflammatory conditions with increased susceptibility to DSS‐ and TNBS‐colitis in Il34−/− animals." (PMID 36030499, 2022). "We also observed that DSS‐induced colitis in Il34−/− rats led to increased levels of pro‐inflammatory cytokines Il6, Il1b, Il22 and a trend for an increase for Il17a, all involved in gut inflammation, whereas Ifng was decreased." (PMID 36030499, 2022). "In the TNBS‐induced colitis model, we observed a shorter colon length at day 3 in Il34−/− mice compared to Il34+/+ and Il34+/+ control mice, indicating more severe inflammation; however, we did not observe significant differences in weight loss." (PMID 36030499, 2022). "Gaining insights towards the role of IL‐34 in T cell development/function, we next assessed the impact of the global deficiency in an inflammatory environment using the acute DSS colitis model." (PMID 36030499, 2022). "In this context, it is noteworthy that studies in rats and mice deficient in IL-34 have documented the enhanced production of multiple auto-antibodies and increased susceptibility to DSS- and TNBS-colitis, probably reflecting defects in regulatory cells (Tregs)." (PMID 39451216, 2024). "Dual blockade of CSF1 and IL34 was slightly more efficacious at preventing disease in DSS colitis than the monotherapies, reducing the histology score compared to the control treatment but was less efficacious than the treatment with CSA, which reduced the histology score by >50%." (PMID 31552020, 2019). "In the present study, we demonstrate distinct expression patterns of IL34 and CSF1 in human normal intestine, regulation of IL34 and CSF1 with inflammation in human IBD and a mouse model of colitis, and identify intestinal epithelial cells as a cellular source of IL-34." (PMID 25896238, 2015). "Further analysis of such samples revealed that the induction of DSS-colitis was associated with enhanced expression of both IL-34 and BRD4, and samples extracted from colonic specimens of mice treated with JQ1 had a significant reduction in RNA transcripts for IL-34." (PMID 39451216, 2024). "IL-34 expression was reduced in IBD LPMCs transfected with BRD4 antisense oligonucleotide and in the colons of mice with dextran sulfate sodium-induced colitis treated with JQ1, a pharmacological inhibitor of BRD4." (PMID 39451216, 2024). "To further confirm the positive regulation of BRD4 on IL-34 expression in the gut, we analyzed the expression of the two proteins in the colons of mice with DSS-induced colitis." (PMID 39451216, 2024). "Up-regulation of both IL-34 and M-CSF-1 was documented in the colons of mice with dextran sulfate sodium (DSS)-colitis." (PMID 35529879, 2022). "In the light of the increased IL34 and CSF1 expression in the inflamed intestine of patients with IBD, we next assessed their involvement in the widely used DSS model of murine colitis." (PMID 25896238, 2015). "Altogether, our data demonstrate that the lack of IL‐34 upon DSS‐induced colitis increases its severity." (PMID 36030499, 2022). "Both IL34 (only trended) and CSF1 were increased in mouse DSS-induced colitis." (PMID 31552020, 2019). "In the present paper, we investigated the expression of IL34, CSF1 and their shared receptor CSF1R in normal human ileum and colon, in inflamed and non-inflamed tissues of CD and UC patients, and in a mouse model of experimental colitis." (PMID 25896238, 2015). "However, in DSS colitis or TNFΔARE ileitis, the blockade of CSF1 and IL34 is most beneficial." (PMID 31552020, 2019).
COVID-19 (6 papers, 2021 to 2025). A disease caused by infection with severe acute respiratory syndrome coronavirus 2. "IL-32 and IL-34 levels on admission were collected and tested for their association with CV disease and short-term mortality in patients with COVID-19." (PMID 36769623, 2023). "As a result of our study, a valuable result has been obtained regarding the use of IL-34 in the evaluation of SARS-Cov-2 and similar infections." (PMID 38626032, 2024). "Depending on the underlying pathophysiological mechanisms of IL-32 and IL-34 release in COVID-19, one may suggest that these biomarkers can be of prognostic value if measured at a different time point." (PMID 36769623, 2023). "Thus, the primary aim of our study was to evaluate an association between IL-32/IL-34 with CV disease in the context of COVID-19." (PMID 36769623, 2023). "Furthermore, one investigation demonstrated that severe acute respiratory syndrome coronavirus 2 (SARS-CoV-2) infection significantly increases human IL-34 levels." (PMID 40176879, 2025). "In patients with COVID-19, plasma IL-34 levels correlated positively with CRP (r = 0.636, p = 0.029)." (PMID 38626032, 2024). "In our study, significant elevation of IL-34 with CRP in COVID-19 seems to be compatible with previously reported results in terms of elevation of IL-34 in infections and inflammatory processes." (PMID 38626032, 2024). "We wanted to evaluate the possible relationship between IL-34 and COVID-19 disease severity, SARS occurrence, and prognosis." (PMID 38626032, 2024). "In our study, we aimed to determine the role of IL-34 in the specific case of COVID-19, based on the roles of IL-34 in inflammatory, cytokine, and immune response, which have been identified in previous studies." (PMID 38626032, 2024). "Again, we planned to compare IL-34 with the other parameters used in the diagnosis, follow-up, and prognosis evaluation of COVID-19." (PMID 38626032, 2024). "IL-34 was elevated in correlation with CRP in COVID-19-positive cases, and higher accuracy rates were also observed than CRP." (PMID 38626032, 2024). "Our study has provided important outputs in determining the role of IL-34 in COVID-19 and should be supported by further studies." (PMID 38626032, 2024). "As a result, IL-34 levels were found to be statistically significantly higher in COVID-19 patients compared to the control group and IL-34 was considered successful in predicting the diagnosis of COVID-19." (PMID 38626032, 2024). "Our study aims to determine the role of IL-34 in the diagnosis, follow-up, and prognosis of Coronavirus Disease-19 (COVID-19)." (PMID 38626032, 2024). "The multivariate analysis with adjustment for potential confounding variables revealed that higher IL-34 and CRP levels were independently associated with COVID-19." (PMID 38626032, 2024). "While this represents the general hospitalized COVID-19 patient population well, it is possible that dynamics of IL-32 and IL-34 are different in pre-specified populations, such as patients requiring intensive care treatment upon admission." (PMID 36769623, 2023). "We also assessed the prognostic impact of IL-32/IL-34 and CV disease on short-term mortality in our well-defined study population of hospitalized patients with COVID-19." (PMID 36769623, 2023). "We believe that IL-34 would be secreted by infiltrating inflammatory leucocytes, particularly macrophages and lymphocytes following the cytokine storm in COVID-19 patients." (PMID 34422917, 2021). "However, only one study was found in the literature review related to the role of IL-34 in COVID-19." (PMID 38626032, 2024). "In our study, IL-34 was found to be successful in predicting the diagnosis of COVID-19." (PMID 38626032, 2024). "IL-34 levels increased in correlation with CRP in predicting the diagnosis of COVID-19." (PMID 38626032, 2024).
COVID-19 (continued). "In addition, although IL-34 was elevated in COVID-19 infection, levels appeared to be undifferentiated in patients with COVID-19 lung involvement and in ICU patients." (PMID 38626032, 2024). "IL-34 levels higher than 31.75 pg/m predicted a diagnosis of COVID-19." (PMID 38626032, 2024). "In addition it has been understood that IL-34 plays a role in the immunopathogenesis of COVID-19 along with other cytokines, and this will guide further studies." (PMID 38626032, 2024). "Based on these results, studying IL-34 in people who apply to clinics with the suspicion of COVID-19 may be useful in supporting and predicting the diagnosis, and its use in clinical routine may be possible." (PMID 38626032, 2024). "IL-32 and IL-34 were neither associated with CV disease nor with clinical endpoints in the context of COVID-19." (PMID 36769623, 2023). "Both interleukin-32 (IL-32) and interleukin-34 (IL-34) have been hypothesized to contribute to CV involvement in COVID-19." (PMID 36769623, 2023). "However, it is valuable as it is one of the rare studies on IL-34 in COVID-19." (PMID 38626032, 2024). "Additionally, IL-34 induction has been observed in patients with influenza infection, which may also be a potential pathophysiological link to COVID-19." (PMID 36769623, 2023). "In addition, we speculate that the role of IL-32 and 37 may also be beneficial, but IL-34 may be harmful, during the course of COVID-19." (PMID 34422917, 2021). "IL-34, CRP, D-dimer, TnI, and ferritin levels were statistically significantly higher; albumin levels were statistically significantly lower in the COVID-19-positive group compared to the control group (p<0.05)." (PMID 38626032, 2024). "We noted stronger upregulation of IL34, a macrophage growth and survival factor, in the Non-COVID-19 and Post-Vaccination groups than in the Post-COVID-19 group." (PMID 39994453, 2025). "According to the results of our study on this subject, IL-34 increased significantly in COVID-19 positivity and predicted the disease, but did not provide clear information in terms of lung involvement, risk of intensive care hospitalization, and prognosis." (PMID 38626032, 2024). "But, in patients with COVID-19, plasma IL-34 levels did not correlate with pulmonary infiltration (r = 0.124, p = 0.48)." (PMID 38626032, 2024). "Furthermore, we observed that the major transcript of multiple genes switched to a different transcript (isoform switching) between COVID-19 patients and controls, such as IL2, IL34, SERPINE2, NCBP1, HRAS, PRPF6, NCBP2, and LUC7L2." (PMID 35421082, 2022). "IL-34 levels were significantly higher in the COVID-19-positive group than in the negative group." (PMID 38626032, 2024).
giant cell tumor (6 papers, 2011 to 2023). A benign, intermediate, or malignant tumor that arises from the bone or soft tissue. "IL-34 acts similarly to MCSF in promoting osteoclastic differentiation of giant cell tumours, but IL-34 also displays singular function during brain development." (PMID 32765828, 2020). "For example, IL-34 promotes osteoclastogenesis and appears to be involved in giant cell tumors of bone." (PMID 29423057, 2018). "The co-expression of both IL-34 and M-CSF has been previously observed in cancers such as giant cell tumors and malignant pleural mesothelioma." (PMID 29323162, 2018). "Previous evidence had demonstrated that IL-34, both from giant cell tumors and gingival fibroblasts, plays a critical role in RANKL-induced osteoclast formation as a complete substitute for CSF-1 and that the systemic administration of IL-34 would result in a decrease in trabecular bone mass." (PMID 29326938, 2017).
leukemia (6 papers, 2020 to 2023). A malignant (clonal) hematologic disorder, involving hematopoietic stem cells and characterized by the presence of primitive or atypical myeloid or lymphoid cells in the bone marrow and the blood. "Signaling through CSF-1R, the major receptor of IL-34, is vital for the differentiation and survival of mononuclear phagocytes; and macrophages play important roles in malignancies including leukemia." (PMID 37149693, 2023). "IL-34 induces differentiation of leukemia cells into mature macrophages, while additionally enhancing differentiation of other cancers." (PMID 35347503, 2023). "This work contributes to a better understanding of AMoL progression, elucidating the roles of IL-34 in leukemia and providing clues for potential targets against leukemia." (PMID 35402828, 2021). "Moreover, using a human leukemia model, IL-34 enhanced the differentiation of leukemia cells into differentiated macrophages by means of an increase in CD14 or CD68 and a decrease in CD71, a cell surface marker for immature myeloid cells." (PMID 33408768, 2021). "Until now, the role of IL-34 in leukemia, especially on LSCs, remains unknown." (PMID 37149693, 2023). "In conclusion, we demonstrate that IL-34 overexpressed in AML cells accelerates AML progression by affecting both AML cell themselves and LAMs in the leukemia microenvironment." (PMID 37149693, 2023). "However, the role of IL-34 in leukemia has not been established." (PMID 37149693, 2023).
periodontitis (6 papers, 2013 to 2025). An acute or chronic inflammatory process that affects the tissues that surround and support the teeth. "Notably, anti-IL-34 neutralizing monoclonal antibodies reduced the number of osteoclasts and attenuated alveolar bone loss in periodontitis lesions." (PMID 40724937, 2025). "Moreover, local injections of mouse recombinant IL-34 significantly increased the number of osteoclasts, enhanced alveolar bone loss, and elevated cathepsin K activity in a mouse model of ligature-induced periodontitis." (PMID 40724937, 2025). "The fact that gingival fibroblast produce both M-CSF and IL-34 in response to pro-inflammatory cytokines, and that these molecules can contribute to recruitment of bone resorbing osteoclasts further points at a pivotal role for gingival fibroblast in inflammation driven bone loss in periodontitis." (PMID 24339952, 2013). "After periodontitis, IL-34 promotes monocyte development toward macrophages, and macrophages secrete a series of cytokines, such as IL-6 and TNF-α, mediating the inflammatory response." (PMID 36879647, 2023). "This study was devoted to demonstrating the role of IL-31 and IL-34 in the diagnosis and treatment of chronic periodontitis (CP)." (PMID 36879647, 2023). "The expression of IL-31 and IL-34 in the gingival tissue of patients with severe periodontitis was significantly higher than that of patients with mild periodontitis, indicating that IL-31 and IL-34 may be closely related to the severity of periodontitis." (PMID 36879647, 2023). "IL-34 may contribute to inflammation and osteoclastogenesis in bone-degenerative diseases such as periodontitis." (PMID 24339952, 2013). "Interleukin-1 beta (IL-1β), sclerostin, osteoprotegerin (OPG), and interleukin-34 (IL-34) emerged as significant biomarkers in GCF, and they were mainly from periodontitis and osteoporosis." (PMID 39410587, 2024). "Finally, IL-34 can promote the formation of osteoclasts by combining with M-CSFR, leading to bone resorption and thus accelerating the development of periodontitis." (PMID 36879647, 2023).
Sepsis (6 papers, 2020 to 2025). Sepsis is defined as life-threatening organ dysfunction caused by a dysregulated host response to infection. "Kaplan-Meier survival curves and multivariate COX regression analysis revealed that IL-34 is an independent risk factor for death within 28 days of sepsis." (PMID 40176879, 2025). "In conclusion, IL-34 has been identified as an independent risk factor for predicting 28-day mortality in sepsis patients." (PMID 40176879, 2025). "Our findings regarding IL-34 align with these observations: IL-34 is associated with sepsis severity and poor prognosis." (PMID 40176879, 2025). "Spearman correlation analysis was employed to examine the relationship between IL-34 levels and scores indicative of sepsis severity, as well as associated inflammatory biomarkers." (PMID 40176879, 2025). "For future research, we recommend further examination of the use of IL-34 in conjunction with established biomarkers to enhance early diagnosis and risk stratification of sepsis." (PMID 40176879, 2025). "For instance, Jacobs and Wiersinga (2018) discussed IL-34 as an emerging factor in sepsis, proposing that it may influence pathogenic processes related to systemic inflammation and organ dysfunction." (PMID 40176879, 2025). "Additionally, Jacobs and Wiersinga (2018) identified IL-34 as an emerging factor in sepsis, suggesting its potential influence on pathogenic processes related to systemic inflammation and organ dysfunction." (PMID 40176879, 2025). "IL-34 shows promise as an independent prognostic factor in sepsis patients and may enhance risk stratification, especially in those with sepsis-induced ALI." (PMID 40176879, 2025). "Our findings also suggest that IL-34 may serve as a valuable risk stratifier for sepsis-induced ALI." (PMID 40176879, 2025). "Additionally, the results from the Kaplan-Meier survival analysis and the multifactorial Cox regression model indicated that IL-34 functions as an independent risk factor for 28-day mortality in sepsis patients, establishing a critical threshold of 130.05 pg/mL for identifying high-risk individuals." (PMID 40176879, 2025). "Another notable difference is that our study demonstrates a positive correlation between serum IL-34 levels and IL-6, PCT, and lactate levels during the onset of sepsis patients, which is also associated with prognosis." (PMID 40176879, 2025). "It is important to clarify that this study does not seek to diminish the significance of established biomarkers; rather, it aims to explore the novel and understudied role of IL-34 in sepsis." (PMID 40176879, 2025). "The current study identifies IL-34 as an independent prognostic factor for survival in sepsis patients." (PMID 40176879, 2025). "We measured the levels of IL-34 in the serum of 115 sepsis patients and 28 healthy individuals, finding that the levels of IL-34 in sepsis patients were significantly elevated compared to those in healthy individuals." (PMID 40176879, 2025). "Recent studies have underscored the relationship between IL-34 and sepsis, illustrating its potential role in mediating immune responses." (PMID 40176879, 2025). "This study aimed to evaluate the potential of interleukin-34 (IL-34) as a novel biomarker for predicting mortality in sepsis patients, with a specific focus on those with sepsis-induced acute lung injury (ALI)." (PMID 40176879, 2025). "Serum IL-34 levels were significantly elevated in sepsis patients compared to healthy controls, and they were also higher in non-survival group compared to survival group (p < 0.05)." (PMID 40176879, 2025). "We recorded serum IL-34 levels in 22 sepsis patients on the first, third, and fifth days to monitor changes." (PMID 40176879, 2025). "The results indicated that, after adjusting for these confounding factors, the hazard ratio for IL-34 remained close to 1, underscoring the necessity for further studies on its prognostic value in sepsis-induced ALI." (PMID 40176879, 2025).